MIR494 (microRNA 494)
Synonyms: hsa-mir-494; MIRN494; mir-494
Gene: MicroRNA gene on chromosome 14 (101,029,634 to 101,029,714, forward strand). Ensembl gene ENSG00000194717.
Gene Ontology:
Biological process: miRNA-mediated post-transcriptional gene silencing
Cellular component: RISC complex
Homologues: Orthologues: chimpanzee ptr-mir-494 (100% identical), dog MIR494 (100% identical), guinea pig MIR494 (99% identical), macaque mml-mir-494 (99% identical), mouse Mir494 (99% identical), rat Mir494 (99% identical). Paralogues in human: MIR154 (78% identical), MIR539 (78% identical), MIR487A (75% identical), MIR382 (72% identical), MIR1185-1 (68% identical), MIR496 (68% identical), MIR323B (67% identical), MIR487B (67% identical), MIR1185-2 (65% identical), MIR323A (65% identical), MIR377 (63% identical), MIR381 (63% identical), and 4 more.
Diseases named in the same sentence as MIR494 in open-access papers:
MIR494 is named in the same sentence as 1 disease in open-access papers, as found by Europe PMC text mining. Sharing a sentence is not in itself a finding about the gene and the disease. The quoted sentences say what the papers report.
renal carcinoma (1 paper, 2016). A carcinoma arising from the epithelium of the renal parenchyma or the renal pelvis. "Herein, we now demonstrate that MIR494 leads to a marked reduction in cell growth in 769-P renal cancer cells which is associated with lipid droplets, reduced total cholesterol levels, and mitochondrial changes." (PMID 26794413, 2016). "Herein, we demonstrate that expression of MIR494 in the 769-P renal cancer cell line reduces cellular viability coinciding with increased LC3B RNA and protein." (PMID 26794413, 2016). "Our findings reported herein demonstrate that MIR494 expression leads to reduced cellular viability in 769-P renal cancer cells." (PMID 26794413, 2016). "MIR494 expression reduces viability of 769-P renal cancer cells; this was accompanied by increased cleaved PARP (an apoptotic marker) and LC3B protein." (PMID 26794413, 2016). "Collectively, these findings implicate MIR494 expression in reducing renal cancer cell survival accompanied by increased lipid droplet formation and mitochondrial changes." (PMID 26794413, 2016). "It is presently unknown whether MIR494, located at 14q32 which is deleted in renal cancers, reduces cell survival in renal cancer cells and if this process is accompanied by changes in the number of lipid droplets." (PMID 26794413, 2016).